BRIP1 (BRCA1 interacting DNA helicase 1)
Diseases named in the same sentence as BRIP1 in open-access papers (continued):
Sharing a sentence is not in itself a finding about the gene and the disease.
rectal cancer (2 papers, 2015 to 2025). A primary or metastatic malignant neoplasm that affects the rectum. "In rectal cancer, a higher BRIP1 expression was significantly associated with younger age (59.5% vs. 41.0%, p = 0.021)." (PMID 41597333, 2025). "As revealed through TCGA data, a higher BRIP1 expression was significantly associated with younger age in rectal cancer." (PMID 41597333, 2025). "Kaplan–Meier survival analyses demonstrated that lower BRIP1 expression was associated with poorer overall survival in both colon and rectal cancers, supporting a prognostic association." (PMID 41597333, 2025). "In rectal cancer, patients with high BRIP1 expression exhibited markedly longer overall survival compared with those with low expression (3324.42 ± 269.84 vs. 1305.64 ± 98.40 days; χ2 = 13.94; p < 0.001)." (PMID 41597333, 2025).
skin cancer (2 papers, 2014 to 2025). "The evidence linking BRCA1/2, ATM, CHEK2, BRIP1, and FH pathogenic variants to increased skin cancer risk is limited." (PMID 41331641, 2025). "The BRIP1 germline mutation was first linked to skin cancer in a family with a rare, likely pathogenic variant associated with MM." (PMID 41331641, 2025).
small cell lung carcinoma (2 papers, 2022 to 2024). Small cell lung cancer (SCLC) is a highly aggressive malignant neoplasm, accounting for 10-15% of lung cancer cases, characterized byrapid growth, and early metastasis. "Next, in small-cell lung cancer, a patient harboring a germline mutation of BRIP1 achieved a notable disease response to DNA repair-targeted therapies." (PMID 36324591, 2022).
stomach adenocarcinoma (2 papers, 2018 to 2020). "In analyses of individuals with East Asian ancestry, we identified an association for BRIP1 in stomach adenocarcinoma (STAD)." (PMID 32471518, 2020). "In the East Asian ancestry, we discovered one previously known association of BRIP1 in stomach adenocarcinoma (OR = 12.8 [95% CI, 1.8–90.8]; FDR = 0.038)." (PMID 32471518, 2020).
uterine corpus endometrial carcinoma (2 papers, 2018 to 2023). A endometrial carcinoma (disease) that involves the body of uterus. "Patients with uterine corpus endometrial carcinoma presented with the highest alteration frequency of BRIP1 (nearly 10%)." (PMID 36907870, 2023).
alcoholic cirrhosis (1 paper, 2017). "In our study, BRIP1 variants were associated with HCC risk in patients with viral cirrhosis but not among those with alcoholic cirrhosis." (PMID 28968953, 2017). "In the Derivation#1 study, the BRIP1 locus reached array-wide significance (Chi-squared SV-Perm, P=5.00×10−4) among the 253 haplotype blocks tested for their association with HCC risk, in patients with viral cirrhosis but not among those with alcoholic cirrhosis." (PMID 28968953, 2017).
angiosarcoma (1 paper, 2025). A malignant tumor arising from the endothelial cells of the blood vessels.
cervical adenocarcinoma (1 paper, 2017). An adenocarcinoma arising from the cervical epithelium. "Using immunohistochemistry assay, BRIP1 expression was observed to be reduced in cervical adenocarcinoma compared with normal cervix tissue and was correlated with unfavorable outcome including lymph node metastases." (PMID 28968953, 2017).
cervical tumors (1 paper, 2014). "Our results revealed an increased protein level of FANCD2, RAD51, BRCA1 and BRIP1 in the NCR compared to CR cervical tumor nuclei." (PMID 24708616, 2014). "We observed a significantly increased protein levels of FANCD2, BRCA1, RAD51 and BRIP1 in the nuclei of the NCR compared to the CR cervical tumors." (PMID 24708616, 2014).
Cirrhosis (1 paper, 2017). A chronic disorder of the liver in which liver tissue becomes scarred and is partially replaced by regenerative nodules and fibrotic tissue resulting in loss of liver function. "In fact, BRIP1 variants were associated with HCC risk even after adjusting for cirrhosis duration in logistic regression analysis and also in Cox's time-dependent proportional hazards regression analysis." (PMID 28968953, 2017). "Nevertheless, BRIP1 variants were independently associated with HCC risk even after adjusting for age and cirrhosis duration." (PMID 28968953, 2017).
cleft lip (1 paper, 2021). Congenital defect in the upper lip where the maxillary prominence fails to merge with the merged medial nasal prominences. "Another study also shows that the genetic variants in other DDR components including BRIP1 may contribute to the risk of non-syndromic cleft lip and palate." (PMID 33854442, 2021).
colorectal tumor (1 paper, 2025). "We hypothesized that reduced BRIP1 expression reflects impaired DDR function in colorectal tumors and is associated with more aggressive clinicopathological features and unfavorable clinical outcomes." (PMID 41597333, 2025).
endometrioid carcinoma (1 paper, 2021). "Most PVs had a high-grade serous (HGS) histology except one BRCA1 with grade 3 endometrioid carcinoma and one BRIP1 with mixed epithelial adenocarcinoma." (PMID 34503154, 2021).
endometrioid endometrial adenocarcinoma (1 paper, 2023). "We present a unique case of a patient with recurrent stage IVB poorly differentiated endometrioid endometrial adenocarcinoma with multiple somatic gene mutations including BRIP1, who had a pathologic complete response following compassionate use of Olaparib for 3 years." (PMID 37298034, 2023).
Esophageal atresia (1 paper, 2022). A developmental defect resulting in complete obliteration of the lumen of the esophagus such that the esophagus ends in a blind pouch rather than connecting to the stomach. "Patient I7 had a pathogenic variant of BRIP1 (OMIM: *605882), a known gene associated with esophageal atresia (OMIM: 189960), and she had vagina mediastinum in our record." (PMID 36361644, 2022).
esophageal squamous cell carcinoma (1 paper, 2023). Esophageal squamous cell carcinoma (ESCC) is a type of esophageal carcinoma (EC) that can affect any part of the esophagus, but is usually located in the upper or middle third.
Hodgkins lymphoma (1 paper, 2018). A heterogeneous group of malignant lymphoid neoplasms of B-cell origin characterized histologically by the presence of Hodgkin and Reed-Sternberg (HRS) cells in the vast majority of cases.
leukemia (1 paper, 2025). A malignant (clonal) hematologic disorder, involving hematopoietic stem cells and characterized by the presence of primitive or atypical myeloid or lymphoid cells in the bone marrow and the blood. "The LOH in the BRIP1 p.(Pro47Ala) variant provides evidence of causality for this patient’s leukemia." (PMID 40766138, 2025).
liver cancer (1 paper, 2023). An epithelial or non-epithelial malignant neoplasm that arises from the liver. "In addition, a positive correlation was found between high BRIP1 expression and worse OS (P=0.021), PFS (P<0.01), RFS (relapse-free survival) (P=0.047), and FP (P<0.001) prognosis for liver cancer." (PMID 36907870, 2023).
liver disease (1 paper, 2017). "Association between the BRIP1 locus and HCC risk suggests that impaired DNA mismatch repair might play a role in liver carcinogenesis, among patients with HCV- or HBV-related liver disease." (PMID 28968953, 2017).
oral cancer (1 paper, 2025). "The upregulation of biomarkers such as Ki67 (antigen Kiel 67) and downregulation of BRIP1 (BRCA1-interacting protein 1), E-cadherin, and cleaved caspase-3 in diabetic patients were suggestive of acceleration of oral cancer progression in conditions of hyperglycemia." (PMID 40028480, 2025).
ovarian adenocarcinoma (1 paper, 2025). An adenocarcinoma that arises from the ovary. "The BRCA1/BRIP1 GDH patient is a 46-year-old female diagnosed with advanced ovarian adenocarcinoma at clinical stage FIGO IVB, exhibited severe chemotherapy-induced toxicity and postoperative complications, including chylous leakage." (PMID 40777133, 2025).
ovarian serous carcinoma (1 paper, 2021). "Our study reported a nonsense BRIP1 variant in a patient with ovarian serous carcinoma." (PMID 34026625, 2021).
ovarian serous cystadenocarcinoma (1 paper, 2023). A malignant serous cystic epithelial neoplasm arising from the ovary. "BRCA1 interacting helicase 1 (BRIP1) alteration was crucial in tumors and it was a potential therapeutic target in ovarian serous cystadenocarcinoma (OV)." (PMID 36932143, 2023).
pancreatic adenocarcinoma (1 paper, 2023). "Data of disease-free survival (DFS) analysis indicated that high expression of BRIP1 was correlated to poor DFS prognosis of ACC, LGG, LIHC, PAAD (pancreatic adenocarcinoma), and THCA (P<0.05 for all)." (PMID 36907870, 2023).
paraganglioma (1 paper, 2023). A benign or malignant neoplasm arising from paraganglia located along the sympathetic or parasympathetic nerves. "Significantly different BRIP1 expression was observed in various molecular subtypes of BRCA, LGG, PCPG (pheochromocytoma and paraganglioma), COAD, LUSC, STAD, HNSC, KIRP, OV, UCEC (P<0.001 for all), LIHC (P<0.01), SKCM, and ESCA (P<0.05 for all)." (PMID 36907870, 2023).
radial dysplasia (1 paper, 2023). "Interestingly, a BRIP1 compound heterozygous genotype consisting of the p.Arg798Ter stop-gain and p.Leu680PhefsTer9 frameshift variants was deemed causative in a clinical sequencing setting in Iceland in a fetus diagnosed with radial dysplasia in utero." (PMID 37301908, 2023).
radiation pneumonitis (1 paper, 2016). Inflammation of the lung due to harmful effects of ionizing or non-ionizing radiation. "Another missense SNP, BRIP1:rs4986764, which was associated with increased risk of radiation pneumonitis." (PMID 26901225, 2016).
secondary hypertension (1 paper, 2021). High blood pressure caused by an underlying medical condition. "Herein, the authors present a case report of a patient with hereditary BRCA1 interacting protein C-terminal helicase 1 (BRIP1) mutation, spindle cell hemangioma, and secondary hypertension caused by atypically localized reninoma." (PMID 33546375, 2021).
serous adenocarcinoma (1 paper, 2021). An adenocarcinoma that is characterized by the presence of papillary patterns and cellular budding. "It has been reported that ~18% of OC, particularly high-grade serous adenocarcinoma, is caused by germline genetic variants such as BRCA1/2, BRCA1-interacting protein C-terminal helicase 1 (BRIP1), and RAD51 paralog D (RAD51D)." (PMID 34064977, 2021).
cancer (194 papers, 2005 to 2026). A tumor composed of atypical neoplastic, often pleomorphic cells that invade other tissues. "Materials and Methods: Families harbouring PVs in RAD50, RAD51C, RAD51D, and BRIP1 were identified by analysing a cancer-predisposing genes panel using Ion S5 system technology." (PMID 40282418, 2025). "Considering the presumed role of BRIP1 in the HR-cascade, studies have explored the significance of BRIP1 as a cancer susceptibility gene." (PMID 40988318, 2025). "Other mutations responsible for the development of this cancer are germline mutations in the BRIP1, RAD51C, or RAD51D genes." (PMID 40429755, 2025). "Emerging evidence also points to additional FA genes, such as RAD51D, FANCM, and FANCJ/BRIP1, as contributors to cancer risk in the heterozygous state." (PMID 41155398, 2025). "Limited but growing evidence suggests a potential clinical benefit of PARP-inhibitors in patients with one of the classical HRD-associated cancer types, in whom a BRIP1-mutation has been identified." (PMID 40988318, 2025). "There is growing evidence suggesting a potential clinical benefit of PARP inhibitors in patients with one of the classical HRD‐associated cancer types, in whom a BRIP1 mutation has been identified." (PMID 41473825, 2025). "Some other genes, like CHEK2, ATM, PALB2, and BRIP1, show a modest tendency for BC; however, patients with these genes' mutations have 2–3 times the high risk of developing a malignant tumor." (PMID 40755497, 2025). "A review of the available literature highlights the importance of BRIP1 in the homologous recombination repair pathway and its role as a cancer susceptibility gene." (PMID 40988318, 2025). "There are also studies evaluating the association between different BRIP1 variants and cervical cancer risk, a genetic susceptibility to this cancer." (PMID 39767562, 2024). "The total alteration frequency of BRIP1 across all tumor types was relatively low (2.21%), and mutation took up a major portion in most cancer types." (PMID 36932143, 2023). "Subsequently, 242 BRIP1 somatic mutations across 32 cancers were further stratified according to their locations in functional domains." (PMID 36932143, 2023). "In the current study, we utilized multiple algorithms to explore the association between immune cell infiltration and BRIP1 expression across different cancers." (PMID 36907870, 2023). "What was noteworthy was that PRAD was the only cancer type in which FDA had approved inhibitors targeted BRIP1 mutation." (PMID 36932143, 2023). "Either from OS or DSS, as well as from DFI and PFI, we found a significant correlation between BRIP1 expression and survival probability in various cancers, among which, BRIP1 was basically a high-risk factor." (PMID 37153833, 2023). "Lastly, as a redundant protein, the significance of the BRIP1 mutation in cancers remains to be further clarified." (PMID 36907870, 2023). "In the current study, we explored BRIP1 expression, methylation, alteration, and their clinical associations in 32 cancer types." (PMID 36932143, 2023). "As a consequence, 231 cases with BRIP1 somatic mutations accompanied with CNVs were found in 32 cancer types." (PMID 36932143, 2023). "Then, we explored the association between BRIP1 expression and its methylation in various cancer types." (PMID 36932143, 2023). "The cancer susceptibility gene BRIP1, as well as COPS2, part of the COP9 signalosome, have both been implicated in DNA damage repair, and were associated with treatment failure and dismal prognosis." (PMID 36333584, 2022). "Previous studies have also demonstrated that biallelic loss in BRIP1 or RAD51D is associated with a higher gwLOH score in BRCA-associated cancers." (PMID 35643464, 2022). "A population-based study by OCAC investigating sporadic cancer cases estimated that carriers of BRIP1 variants had a relative risk of 11.2 for OC (95%CI = 3.2–34.1; p = 1 × 10−4), but not for BC." (PMID 34298626, 2021).
cancer (continued). "Although pathogenic mutations and a large number of missense mutations in BRIP1 have been discovered through genetic testing, the impact of these mutations on the molecular function and subsequent role of BRIP1 in cancer risk is uncertain." (PMID 34408776, 2021). "It is observed that the genetic polymorphisms in BRIP1 influence the cancer susceptibility by altering their natural function." (PMID 29466248, 2018). "Of the 7325 women with American-European ancestry who remained cancer-free until at least 70 years of age, 9 (0.12%) carried heterozygous BRIP1 LoF mutations." (PMID 29368626, 2018). "According to the stratified analysis by ethnicity, the rs2048718, rs4988344, rs4986764 and rs6504074 polymorphisms of BRIP1 were strongly related to cancer susceptibility among Chinese population." (PMID 29466248, 2018). "Recently, numerous molecular epidemiology studies explored the relationship between BRIP1 polymorphisms and cancer susceptibility." (PMID 29466248, 2018). "With a sample size of 13,716, our meta-analysis showed the overall associations between common polymorphisms of BRIP1 (rs2048718, rs4988344, rs4986764, and rs6504074) and cancer risk." (PMID 29466248, 2018). "Among these drugs, Poly(adenosine diphosphate ribose) polymerase (PARP) inhibitors have been shown to be effective in cancer patients with mutations in homologous recombination repair genes, including BRIP1." (PMID 28968953, 2017). "BRIP1 is a DNA helicase that directly interacts with the C-terminal BRCT repeat of the breast cancer susceptibility protein BRCA1 and plays an important role in BRCA1-dependent DNA repair and DNA damage–induced checkpoint control." (PMID 24040146, 2013). "Among the various mutation types of BRIP1 in pan-cancer, amplification was the most common type." (PMID 37153833, 2023). "The aberrant expression of BRIP1 is associated with many human diseases, especially cancers." (PMID 36907870, 2023). "Besides, we further explored the genome-wide association of BRIP1 mRNA in cancer by analyzing the correlation between BRIP1 and other genes using the Regulome Explorer." (PMID 36907870, 2023). "Moreover, the distribution diagram of BRIP1 mutations in these three functional domains varied greatly among different cancers." (PMID 36932143, 2023). "Additionally, BRIP1 was intimately correlated with the ESTIMATEScore in 19 cancers and positively associated with TMB in 9 cancers with MSI in 7 cancers, indicating a promising response to ICB therapy in these tumors." (PMID 37153833, 2023). "Previous studies on BRIP1 mutation in cancer were only focused on individual cancer types." (PMID 36932143, 2023). "In the current study, we analyzed BRIP1 abnormal expression, methylation, mutation, and their clinical application via several extensive datasets, which covered over 10,000 tumor samples across more than 30 cancer types." (PMID 36932143, 2023). "This in-depth data-mining based study helped us understand the role of BRIP1 in tumorigenesis, provided evidence for its diagnostic and prognostic evaluation in the clinic, and shed light on the novel targeted treatment as well as immunotherapy in pan-cancer." (PMID 37153833, 2023).